EXOC3 (exocyst complex component 3)
Description:
Component of the exocyst complex involved in the docking of exocytic vesicles with fusion sites on the plasma membrane.
Synonyms: SEC6; SEC6L1; Sec6p
Tractability: PROTAC: ubiquitination databases record sites on it; its protein half-life has been measured.
Gene: Protein-coding gene on chromosome 5 (442,522 to 471,937, forward strand). Ensembl gene ENSG00000180104.
Subcellular location: Cytoplasm; Cytoplasm, perinuclear region; Cell projection, growth cone; Midbody; Golgi apparatus; Cell projection, neuron projection
Subcellular location (Human Protein Atlas): Cytosol; Plasma membrane
Pathways (Reactome):
Metabolism of proteins: Insulin processing
Organelle biogenesis and maintenance: VxPx cargo-targeting to cilium
Vesicle-mediated transport: Translocation of SLC2A4 (GLUT4) to the plasma membrane
Gene Ontology:
Molecular function: cadherin binding; protein binding; SNARE binding
Biological process: exocyst localization; exocytosis; membrane fission; mitotic cytokinesis
Cellular component: midbody; cytoplasm; cytosol; exocyst; secretory granule membrane; Golgi apparatus; growth cone; membrane; neuron projection; perinuclear region of cytoplasm
Genetic constraint (gnomAD): Loss-of-function variants: 21 observed, 63.72 expected, observed/expected ratio (o/e) 0.33, 90% interval 0.23 to 0.47. The upper end of that interval is the gene's LOEUF score, 0.47, which puts it in group 2 of 6, group 1 being the genes least tolerant of losing a copy. Missense variants: 807 observed, 926.56 expected, observed/expected ratio (o/e) 0.87, 90% interval 0.82 to 0.92. Synonymous variants: 392 observed, 371.16 expected, observed/expected ratio (o/e) 1.06, 90% interval 0.97 to 1.15.
Homologues: Orthologues: chimpanzee EXOC3 (99% identical), macaque EXOC3 (99% identical), mouse Exoc3 (96% identical), guinea pig EXOC3 (95% identical), rabbit EXOC3 (95% identical), rat Ahrr (95% identical), dog EXOC3 (94% identical), pig EXOC3 (94% identical), tropical clawed frog exoc3 (79% identical), zebrafish exoc3 (75% identical), Drosophila melanogaster Sec6 (38% identical), Caenorhabditis elegans sec-6 (32% identical). Paralogues in human: EXOC3L1 (28% identical), EXOC3L2 (20% identical), EXOC3L4 (19% identical), TNFAIP2 (18% identical).
Diseases named in the same sentence as EXOC3 in open-access papers:
EXOC3 is named in the same sentence as 24 diseases in open-access papers, as found by Europe PMC text mining. Sharing a sentence is not in itself a finding about the gene and the disease. The quoted sentences say what the papers report.
asthma (2 papers, 2021 to 2025). "For example, higher expression of the Exocyst Complex Component three gene (EXOC3) is associated with an increased risk of asthma." (PMID 34142656, 2021).
Arterial thrombosis (1 paper, 2023). The formation of a blood clot inside an artery. "EXOC3 is important for controlling granule secretion and glycoprotein receptor trafficking in platelets, and in EXOC3 conditional knockout mice arterial thrombosis was found to be accelerated along with improved homeostasis." (PMID 38062110, 2023).
Barrett esophagus (1 paper, 2023). Esophageal lesion lined with columnar metaplastic epithelium which is flat or villiform. "Recently, EXOC3 was identified as a susceptibility locus for Barrett esophagus and esophageal adenocarcinoma." (PMID 37444464, 2023). "EXOC3, a part of the exocyst complex, together with ZNF641, has recently been identified as a susceptibility locus for Barrett esophagus and esophageal adenocarcinoma." (PMID 37444464, 2023).
inflammatory bowel disease (1 paper, 2025). A spectrum of small and large bowel inflammatory diseases of unknown etiology. "Thirteen SNPs (e.g., EXOC3: 6, SLC25A26: 1, YIF1B: 6) and intestinal microbiomes were significant features of the random forest for the prediction of inflammatory bowel disease." (PMID 40941714, 2025).
myeloma (1 paper, 2023). "To test whether exocyst is necessary for the secretion of antibodies in these cells, we used transient CRISPR-Cas9 to KO EXOC3 in a clonal myeloma cell line that secretes complete IgG (both heavy and light antibody chains)." (PMID 36920342, 2023).
infection (3 papers, 2020 to 2025). The state of being infected such as from the introduction of a foreign agent such as serum, vaccine, antigenic substance or organism. "To test this, we examined the localization of EXOC2 and EXOC3 prior to STm infection." (PMID 38600106, 2024). "Here, we observed that EXOC3 but not EXOC2 recruitment is diminished during infection of ΔsopE2 mutant bacteria compared to WT STm." (PMID 38600106, 2024).
cancer (2 papers, 2021 to 2025). A tumor composed of atypical neoplastic, often pleomorphic cells that invade other tissues. "It remains to be investigated whether the chronic activation of inflammatory signaling during aging and carcinogenesis would lead to chronic induction of Tnfaip2/Exoc3‐driven lipid metabolism in tissue‐resident stem cells and how this would affect tissue maintenance and cancer initiation." (PMID 33300287, 2021). "These modules contained several cancer regulators such as Intraflagellar Transport (IFT) complex proteins (IFT74, IFT88), BBSome complex proteins (BBS2, BBS7, BBS9, BBS12), exocyst complex components (EXOC3, EXOC4, EXOC6B, EXOC7, and EXOC8), TTC8, TTC21B, EVC, and NEK1." (PMID 40700427, 2025). "However, TNBC, HER2-enriched and luminal B cancers additionally included exocyst-associated markers (EXOC3, EXOC4, EXOC6B, EXOC7, and EXOC8), which suggested that, unlike luminal A, these cancers not only share dysregulation of ciliogenesis but also dysfunction of transport to cilium." (PMID 40700427, 2025).
tumor (2 papers, 2017 to 2022). "It would be interesting to decipher if EXOC3, which was not validated to be prognostic, could provide some insight into different tumor biology of HNSCC in a Caucasian versus an Asian population." (PMID 29108335, 2017).
kidney (1 paper, 2022). "Many of these genes have been shown to be associated with steady-state, heat tolerance and renal function; for example, EXOC3 maintains organ homeostasis by driving lipid metabolism, FGR causes kidney injury, GPR3 is a receptor gene involved in adipose thermogenesis and MLX regulates metabolism." (PMID 36552284, 2022).
EXOC3 also shares sentences with these, for which no sentence is quoted: Alzheimer disease (1 paper); breast carcinoma (1); cervical cancer (1); cyst (1); esophageal adenocarcinoma (1); insulinoma (1); lung adenocarcinoma (1); lung carcinoma (1); multicystic dysplastic kidney (1); oral squamous cell carcinoma (1); osteosarcoma (1); ovarian carcinoma (1); prostate carcinoma (1); renal cell cancer (1); schizophrenia (1).